TNF (tumor necrosis factor)
Diseases named in the same sentence as TNF in open-access papers (continued):
Sharing a sentence is not in itself a finding about the gene and the disease.
systemic inflammatory response syndrome (continued). "In the early stages of sepsis, a subset of activated macrophages, characterized by their expression of proinflammatory markers such as TNF-α, IL-1β, and IL-6, plays a pivotal role in activating the coagulation and complement systems, thereby inducing systemic inflammatory response syndrome (SIRS)." (PMID 41169382, 2025). "Although multiple studies have shown that caspase-8 can directly cleave pro-IL-1β into mature IL-1β in circumstances such as TNF-α-induced systemic inflammatory response syndrome (SIRS), mature IL-1β fragments were undetectable in caspase-1-deficient macrophages upon nigericin treatment." (PMID 41208996, 2025). "Nec-1 protects mice from TNF-induced lethal systemic inflammatory response syndrome (SIRS)." (PMID 38257794, 2024). "TNF-α is a cytokine released from the myocardium secondary to ischemia-reperfusion injury, and it contributes directly to myocardial dysfunction and the pathogenesis of systemic inflammatory response syndrome (SIRS)." (PMID 38961388, 2024). "Furthermore, patients with systemic inflammatory response syndrome possess higher plasma levels of IL-8, IL-1β, and TNF-α, which induce NET formation in PMN from healthy individuals." (PMID 39749330, 2024). "Factors such as CPB and surgical trauma can activate systemic inflammatory response syndrome and expand its cascade, which promotes release of proinflammatory cytokines such as TNF-α, leading to pulmonary injury after CPB and serious organ dysfunction after surgery." (PMID 37442959, 2023). "Importantly, treatment with HG-9-91-01 protects mice from TNF-induced systemic inflammatory response syndrome (SIRS) and Staphylococcus aureus-mediated lung damage." (PMID 35217652, 2022). "The therapeutic strategy by IL-6, IL-1 or TNF-α pathways which could halt or balance the systemic inflammatory response syndrome (SIRS) or the other such complications." (PMID 35008377, 2022). "IFN-γ, GM-CSF and TNF-α are major cytokines produced by activated NK cells, and have a protective effect during infection but a deleterious effect during aseptic or infectious systemic inflammatory response syndrome." (PMID 36506322, 2022). "Both TNF-α and IL-1β are major players in the hierarchy of proinflammatory mediator cascades, while nitric oxide (NO) and oxygen free radicals are secondary effectors of cardiac depression in systemic inflammatory response syndromes." (PMID 35707040, 2022). "Importantly, mice pretreated with HG-9-91-01 showed resistance to TNF-induced systemic inflammatory response syndrome." (PMID 35217652, 2022). "We utilized a TNF-SIRS mouse model to determine whether PPP6C regulates the onset of systemic inflammatory response syndrome." (PMID 35842423, 2022). "Finally, Ppp1r3g−/− mice are protected from tumor necrosis factor-induced systemic inflammatory response syndrome, confirming the important role of PPP1R3G in regulating apoptosis and necroptosis in vivo." (PMID 34862394, 2021). "Importantly, Zharp-99 exerts effective protection against TNF-α induced systemic inflammatory response syndrome in the mouse model." (PMID 33364238, 2020). "Importantly, PK68 provides strong protection against TNF-α-induced systemic inflammatory response syndrome in vivo." (PMID 31235688, 2019). "Of note, these mice were also greatly protected from a lethal dose of TNF injected in absence of IKKi, a model of Systemic Inflammatory Response Syndrome (SIRS) also caused by RIPK1 kinase-dependent apoptosis and necroptosis." (PMID 30988283, 2019). "Similarly, TNF-α soluble receptor levels were shown to raise in plasma of burn-induced systemic inflammatory response syndrome children whereas IL-13 serum levels remained unchanged." (PMID 29675435, 2018).
systemic inflammatory response syndrome (continued). "Contact and interaction of blood with foreign surfaces during cardiopulmonary bypass (CPB) cause systemic inflammatory response syndrome (SIRS) through activation of several humoral cascades including cytokines such as IL-6, IL-8, and Tumor Necrosis Factor-α (TNF-α)." (PMID 26064103, 2015). "Furthermore, the production of PCT is said to be associated with inflammatory cytokines such as tumor necrosis factor (TNF)-α; it is also considered to be increased in not only infection but also systemic inflammatory response syndrome (SIRS)." (PMID 25908988, 2014). "Interestingly, blocking of IL-17 prior to systemic TNF-α application, protects mice from TNF-α induced systemic inflammatory response syndrome." (PMID 20374638, 2010). "Necrostatin-1 is widely used to inhibit necroptosis in several animal models of inflammation, including LPS and mechanical ventilation-induced ALI, and TNF-induced systemic inflammatory response syndrome (SIRS)." (PMID 40191423, 2025). "The Systemic Inflammatory Response Syndrome (SIRS) is triggered by endotoxin, which stimulates the release of inflammatory cytokines, such as TNF-α; IL-1α/β, and IL-17 into the circulation." (PMID 40821837, 2025). "Central to this process is the cytokine storm, driven by uncontrolled release of TNF-α, IL-1β, and IL-6, which exacerbates systemic inflammatory response syndrome (SIRS) and tissue injury." (PMID 41262247, 2025). "Furthermore, serum acetylcholine (ACh) reduces the production of inflammatory cytokines (TNF-α, IL-1β, IL-6, and IL-18) through the alpha 7 nicotinic acetylcholine receptor subunit (α7nAChR) hereby preventing systemic inflammatory response syndrome (SIRS) development." (PMID 40299464, 2025). "In trauma, systemic inflammatory response syndrome (SIRS), or severe burns, insulin reduces pro-inflammatory mediators (TNF-a, IL-6, CRP, IFN-y, IL-18)." (PMID 39838305, 2025). "Both RIPK1 kinase-driven inflammation and cell death are key contributors to tumour necrosis factor-alpha (TNF-α)-induced systemic inflammatory response syndrome (SIRS)." (PMID 38419035, 2024). "In any case, these compounds represent potent inhibitors of necroptosis, with proven efficacy in the in vivo mouse model of TNF-induced Systemic Inflammatory Response Syndrome (SIRS)." (PMID 37373257, 2023). "We also found that Quizartinib inhibited the activation of RIPK1 and protected mice from TNF-induced systemic inflammatory response syndrome (SIRS)." (PMID 37741898, 2023). "TNF-induced systemic inflammatory response syndrome (SIRS) is the most used models for proving the roles in necroptosis as RIPK3 or MLKL KO mice are resistant." (PMID 35217652, 2022). "In the early stage of ALI, local neutrophils and macrophages infiltrate in the lung tissues and secrete various cytokines like TNF-α, IL-6, and IL-1β, which can further activate leukocytes and cause systemic inflammatory response syndrome (SIRS) if inflammation is not controlled." (PMID 35264058, 2022). "The TNFα-driven shock is a widely used necroptosis-related disease model, leading to systemic inflammatory response syndrome (SIRS)." (PMID 36539410, 2022). "ZBP1-deficient mice were significantly protected in the setting of systemic inflammatory response syndrome (SIRS) induced by TNF and IFN-γ." (PMID 36040212, 2022). "RIPK1 inhibition is also protective in acute disease models such as the TNF-induced systemic inflammatory response syndrome (SIRS) model." (PMID 32999468, 2021). "In addition, in vitro assays with purified proteins showed that CK1γ phosphorylated RIPK3, affecting its activity, and in vivo assays showed that the CK1γ-specific inhibitor Gi prevented abrupt death in mice with hypothermia in a model of TNFα-induced systemic inflammatory response syndrome." (PMID 31801942, 2019). "We thus examined the potential in vivo contribution of CK1γ-mediated necroptosis to a TNFα-induced systemic inflammatory response syndrome (SIRS) mouse model." (PMID 31801942, 2019).
systemic inflammatory response syndrome (continued). "In vivo Sorafenib protects against TNF-induced systemic inflammatory response syndrome (SIRS) and renal ischemia–reperfusion injury (IRI)." (PMID 28661484, 2017). "Cytokines (TNF-α and IL-6) are important components of the immune system because they act as messengers between cells, but they are also involved in many pathological aspects of the cascade leading to systemic inflammatory response syndrome (SIRS) and ultimately MODS." (PMID 28198368, 2017). "Studies on mouse models have also shown that TNF-induced systemic inflammatory response syndrome (SIRS) and CLP-induced peritoneal sepsis are driven by both RIPK1 and RIPK3-dependent necroptosis." (PMID 26491219, 2015). "Studies on mouse models of the TNF-induced systemic inflammatory response syndrome (SIRS) and CLP-induced peritoneal sepsis have shown that multiple organ failure and animal mortality are driven by both RIPK1 and RIPK3-dependent necroptosis." (PMID 25140116, 2014). "In addition, aberrant induction and an imbalance of various proinflammatory cytokines, for example, IL-1β, IL-6, and tumor necrosis factor (TNF), may induce severe systemic inflammatory response syndrome." (PMID 24062733, 2013). "One such clinical condition is severe acute pancreatitis (SAP), during which the levels of endotoxin and the ability of whole blood cells to release TNF-α upon stimulation by LPS fall somewhere between those observed in systemic inflammatory response syndrome (SIRS) and severe sepsis." (PMID 41010682, 2025). "All donkeys developed typical features of a systemic inflammatory response syndrome (SIRS) such as tachycardia, fever, and an increase in plasma TNFα and IL-1β concentrations from 30 min PLI (data previously published)." (PMID 40805061, 2025). "TNF-α is a cytokine protein that exists in both soluble and transmembrane formsas a primary mediator of the systemic inflammatory response syndrome (SIRS) andis believed to be involved in mediating renal insufficiency in various renalconditions following envenoming." (PMID 38808074, 2024). "To demonstrate scalability, we used automated immunohistochemistry to characterize the expression of Caspase-8, RIPK1 and RIPK3 across six tissues during TNF-induced systemic inflammatory response syndrome (SIRS)—a widely-used model of RIPK-dependent pathology." (PMID 38750308, 2024). "SARS-CoV-2 infection can trigger a cytokine storm by activating immune cells, thereby releasing large amounts of cytokines (eg, IL-6 and TNF-α) and leading to systemic inflammatory response syndrome (SIRS) and multi-organ dysfunction (MODS), which often affect the liver." (PMID 39867341, 2024). "Systemic inflammatory response syndrome (SIRS) is the result of an unbalanced inflammatory response that escalates and releases an excessive amount of inflammatory mediators, such as IL-1, IL-6, IL-8, and TNF." (PMID 36900099, 2023). "Several type II kinase inhibitors such as the FDA approved drugs ponatinib and sorafenib, which target RIPK1, also block the kinase activity of RIPK3 and can protect mice from TNF-induced systemic inflammatory response syndrome (SIRS) and renal ischemia-reperfusion injury." (PMID 37409125, 2023). "Via immune activation, DAMPs trigger a systemic inflammatory response syndrome (SIRS) that is characterised in part by elevated circulating concentrations of a range of pro-inflammatory cytokines (Interleukin IL6, Tumor Necrosis Factor α)." (PMID 36471343, 2022). "Gypsum fibrosum reduced the serum levels of TNF-α and IL-6, and IL-1β, TNF-α, and IL-6 in lung tissues in mice with systemic inflammatory response syndrome induced by lipopolysaccharide." (PMID 33693014, 2021). "The excessive stress reaction of immune system would release superabundant cytokines such as TNF-α、IL-1、IL-6、IL-12、IFN-α、IFN-γ, leading to systemic inflammatory response syndrome (SIRS) and multiple organ failure." (PMID 34386017, 2021).
systemic inflammatory response syndrome (continued). "Extracorporeal circulation contributes to AKI because of red blood cell hemolysis and the systemic inflammatory response syndrome (SIRS), that induces the increase in blood levels of mediators, such as IL-6, IL-8 and TNF-α." (PMID 34019579, 2021). "Knock-in mice expressing UBA domain-mutant cIAP1 are more sensitive to TNF-mediated systemic inflammatory response syndrome (SIRS), implying that UBA domain-mediated RIPK1 K48-linked ubiquitination is an important step in modulating the cytotoxic potential of the TNF-mediated response." (PMID 34075202, 2021). "Importantly, pre-treatment of Zharp-99 significantly ameliorates TNF-induced systemic inflammatory response syndrome (SIRS) in the mouse model." (PMID 33364238, 2020). "In animals, exogenous TNF administration leads to a syndrome that is indistinguishable from septic shock and infusion of TNF into humans results in systemic inflammatory response syndrome (SIRS)." (PMID 29751683, 2018). "Serum molecules like IL-1β, IL-6, TNF-α, ICAM-1, and E-selectin were involved in the pathophysiology of systemic inflammatory response syndromes." (PMID 24693284, 2014). "TNF-α is known to be involved in systemic inflammatory response syndrome (SIRS), which usually precedes MOFS in several ill patients, while IL-8 is a specific monocyte attracting chemokines that modulates monocyte activation, an important condition in organ damage and haemostatic complications." (PMID 25132729, 2014). "Activation of local and systemic metabolic response σ to trauma and systemic inflammatory response syndrome (SIRS) is mediated mainly by activation of interleukins (IL) and tumor necrosis factor-α (TNF-α)." (PMID 24605247, 2014). "We hypothesized that AKI and ALI would occur simultaneously due to a shared pathophysiology (i.e., TNF-α mediated systemic inflammatory response syndrome [SIRS]), but that sensitive methods would be required to identify AKI." (PMID 24265742, 2013). "Laboratory findings in the present study revealed abnormally elevated circulating levels of creatinine, TNF-α and white blood cell count as well as notably decreased SBP following CLP-induced sepsis syndrome." (PMID 24451364, 2013). "In this study, we hypothesized that AKI and ALI would occur simultaneously due to a shared pathophysiology (i.e., TNF-α mediated systemic inflammatory response syndrome [SIRS]), but that sensitive markers of kidney function would be required to identify AKI." (PMID 24265742, 2013). "TLR-mediated signaling pathways induce proinflammatory cytokine expression like tumor necrosis factor-alpha (TNF-α) and interleukin-6, triggering the systemic inflammatory response syndrome and the development of septic shock." (PMID 19091080, 2008). "Additionally, Phen mitigated RIPK1-driven inflammation in a murine model of systemic inflammatory response syndrome (SIRS) induced by lipopolysaccharide (LPS) and tumor necrosis factor (TNF)." (PMID 40456737, 2025). "In addition, silencing of miR-21 protects mice from TNF-α-induced systemic inflammatory response syndrome (SIRS), and this process involves silencing of miR-21 to increase the activity of caspase 8, and then downregulating the expression of RIP1/RIP3 to inhibit the formation of microsomes." (PMID 35509084, 2022). "Specifically, we found of significant elevation of the inflammatory cytokines IL-1β, TNF-α, IL-6, and CXCL1 in the peripheral circulation at P10, around human term age equivalent, in POE rats suggesting a systemic inflammatory response syndrome (SIRS)-like response." (PMID 37396628, 2022). "In systemic inflammatory response syndrome (SIRS), TNF-α activates and promotes the Cx43 hemichannel opening in a Ca2+-dependent manner, leading to renal vascular permeability and mortality; however, in the presence of Gap19, a specific Cx43 hemichannel inhibitor, there is a protective effect." (PMID 35806312, 2022).
systemic inflammatory response syndrome (continued). "This is further supported by studies showing that inhibition of necroptosis partially protects mice from systemic inflammatory response syndrome induced by injection of high dose recombinant TNF in the absence of caspase-8 inhibition." (PMID 33858959, 2021). "Abraham used a TNF-α mAb to treat septic shock, while Fisher used an IL-1R antagonist in the treatment of patients with sepsis syndrome; however, the results were not satisfactory." (PMID 25120616, 2014). "For three decades, the production of proinflammatory cytokines, such as IL-1β, IL-6, IL-8, and TNF-α, by leukemic cells in ATRA-differentiated APL patients has been recognized to result in DS and subsequent systemic inflammatory response syndrome (SIRS)." (PMID 41184249, 2025). "Similar findings have been reported in the context of systemic inflammatory response syndrome (SIRS); whereby TRPV1 nociceptors plays an immunosuppressive role by inhibiting production of TNF-α." (PMID 34975876, 2021). "TNF-α and IL-6 aggravate SAP and increase plasma extravasation and induce leukocyte adherence, result in SIRS (the systemic inflammatory response syndrome) and MODS (the multiple organ dysfunction syndrome)." (PMID 28713490, 2017). "Amelioration of systemic inflammatory response syndrome (SIRS) induced by OMV was observed through the administration of salbutamol and nortriptyline, which exhibited inhibitory effects on the release of IL-6 and tumor TNF from macrophages." (PMID 38420121, 2024). "Further it was noted that IL-10 encoding SNP genes were found responsible for exacerbating systemic inflammatory response syndrome (SIRS) score during CAP infection but not the TNF-α and IL-6 cytokines." (PMID 33634060, 2020). "We did not measure circulating levels of IL-6, CRP and TNF-alpha, but we did look for overt manifestations of inflammation through the systemic inflammatory response syndrome (SIRS) criteria." (PMID 31590379, 2019). "GRDim mice are strongly sensitized in models of TNF- and LPS-induced Systemic Inflammatory Response Syndrome (SIRS) and these mice could furthermore no longer be protected by a prophylactic Dexamethasone administration." (PMID 31333672, 2019). "The in vitro release of pro-inflammatory cytokines such as interleukin (IL)-1β, IL-6, IL-8, and tumor necrosis factor-α (TNF-α) have been reported to coincide with ATRA-induced differentiation of APL blasts, which may lead in vivo to a systemic inflammatory response syndrome (SIRS)." (PMID 32859169, 2020). "However, in two large clinical trails, administration of a monoclonal antibody against human TNF-α (TNF-α MAb) and a recombinant human IL-1 (rhIL-1ra) receptor antagonist failed to prolong survival in patients with sepsis syndrome." (PMID 19799777, 2009).